CDK4 (cyclin dependent kinase 4)
Diseases named in the same sentence as CDK4 in open-access papers (continued):
Sharing a sentence is not in itself a finding about the gene and the disease.
glioblastoma (continued). "Glioblastoma is characterized by a high frequency of CDK4/CDK6 pathway dysregulation." (PMID 36900358, 2023). "Furthermore, a separate investigation revealed that the inhibition of CDK4/6 in glioblastoma triggered the activation of the NF-κB-mediated c-Met and TrkA-B pathways." (PMID 37945598, 2023). "Similar results were obtained from other groups, who demonstrated that AGK2 induces growth inhibition in the sub-G0 (pre-G1) phase in glioblastoma cells and in the sub-G0 and G1 phases in cervical cancer cells which were mediated by the decrease in cyclin D1, Cdk4 and Cdk6 expression." (PMID 35406775, 2022). "Currently, abemaciclib and ribociclib, two kinds of CDK4/6 inhibitors, are being explored in phase I trials for pediatric and adult patients with glioblastoma, although palbociclib, a dual CDK4/6 inhibitor, is ineffective in the treatment of recurrent glioblastoma." (PMID 35991838, 2022). "However, CDK2 and CDK4 were positively correlated with tumor purity in skin cutaneous melanomas, LUADs, LIHCs, head and neck cancers, glioblastomas, and breast invasive carcinoma." (PMID 33668805, 2021). "Our findings with tectorigenin, another flavonoid, are in line with these previous observations, as tectorigenin repressed CDK4 expression, reduced the phosphorylation of RB protein, and eventually diminished the proliferation of human glioblastoma GBM-8401 cells." (PMID 33321738, 2020). "Similarly, the flavonoid phloretin increased the production of reactive oxygen species and dose-dependently decreased the expression of CDK2, CDK4, and cyclin D to ultimately inhibit the proliferation of human glioblastoma cells." (PMID 33321738, 2020). "In addition, combining CDK4/6 inhibitors with chemotherapy and radiotherapy was more beneficial to OS than treatment with CDK4/6 or radiation alone in mouse models of AT/RTs, glioblastoma, and non-small cell lung cancer." (PMID 33271970, 2020). "Considering that the pRB signaling is inhibited by kinase activities of the CDK4/CDK6 and Cyclin D complex, the inactivation of CDK4/6 could be a novel anti-glioblastoma treatment option for GBM patients with aberrant expression of pRB." (PMID 33113890, 2020). "It has been reported that the use of CDK4/6 inhibitors can be applied for glioblastoma treatment." (PMID 29161257, 2017). "Outcomes of these studies have been contrasting in terms of PD0332991 efficacy within the brain: more research is necessary to conclude whether CDK4/6 inhibitor can be beneficial in the treatment of glioblastoma." (PMID 26649278, 2015). "Additionally, DYRK1A/B inhibition may sensitize glioblastoma cells to drugs that exert their effects in the G1 phase of the cell cycle, for example CDK4 or MEK inhibitors." (PMID 34708541, 2021). "Glioblastoma (GBM) stem cell-like (GSC) lines were more sensitive to CDK4/6 inhibitors palbociclib and ribociclib than other subtypes." (PMID 34439268, 2021). "Inhibition of the G1 regulating genes CDK4 or Cyclin D1 in glioblastoma cells may lead to the restoration of the G1 checkpoint and subsequent glial differentiation as the cyclin D1-cdk4 axis is the primary gateway through which mitogenic information is channelled." (PMID 24205314, 2013).
glioblastoma (continued). "In glioblastoma, overexpression of CDK2, CDK4, and CDK6 is frequently observed, underscoring their critical role in driving astrocytic tumorigenesis and glioma progression." (PMID 39650055, 2024). "Moreover, the potential role of CDK4 in GBM is reinforced by the fact that both drugs are involved in clinical trials for glioblastoma treatments (DrugBank)." (PMID 36769158, 2023). "In osteosarcoma and glioblastoma, TRPM8 promotes cell proliferation through the modulation of cyclin D1 and cyclin-dependent kinase 4 (Cdk4) expression." (PMID 37033630, 2023). "In conclusion, this preliminary study pointed out for the first time, to the best of our knowledge, the potential role of CDK4 and EXT2 in the peritumoural brain zone of glioblastoma as driver genes forwarding the malignant transformation of this area." (PMID 36769158, 2023). "Another promising therapy is the combination of CDK4/6 and PI3K/mTOR inhibitors for the treatment of recurrent glioblastoma." (PMID 36998447, 2023). "Moreover, another study found that glioblastoma (GBM) xenograft lines with CDKN2A expression and either RB mutation or CDK4 amplification were resistant to palbociclib." (PMID 35892870, 2022). "It is reported that CDK4 and Phosphoinositide 3-kinase enhancer (PIKE-A) are co-localized on chromosomal 12q13.1-14 and co-amplified in glioblastoma and form a protein complex with each other to promote tumorigenesis." (PMID 35463335, 2022). "Both CDK4 and MDM2 are known to be hyper-amplified in glioblastoma, often by double minute chromosomes." (PMID 34891161, 2021). "The CDK4/CDK6 and TUBA1C mRNA levels were higher in glioblastomas than those in normal brain tissues." (PMID 32860670, 2020). "CDK4 and CDK6 activate FOXM1, and FGFR1 appears to be involved in FOXM1 expression since silencing of FGFR1 in glioblastoma cells resulted in downregulation of FOXM1." (PMID 32976773, 2020). "CDK6 is a validated target in the treatment of Glioblastoma, a kind of brain tumor that is characterized by a high frequency of CDKN2A/CCND2/CDK4/CDK6 pathway dysregulation." (PMID 32858868, 2020). "Further, mRNA products of CDK4, CDK6 and α-tubulin were significantly higher in glioblastoma than those in normal tissues, and these results were significantly correlated to pathological grades and clinical prognosis via analyzing TCGA and CGGA databases." (PMID 32860670, 2020). "Genes known to be the most frequently amplified in glioblastoma, EGFR, CDK4, PDGFRA, MDM2, MDM4 are all found to be involved in tumorigenesis of a variety of cancers and are members of several signaling pathways notoriously involved in cancer." (PMID 30871102, 2019). "Dysregulation of retinoblastoma (Rb) signaling pathway have been established as a requirement for glioblastoma (GBM) initiation and progression, which suggests that blockade of CDK4/6-Rb signaling axis for GBM treatment." (PMID 31787897, 2019). "Chromothripsis occurred in 29.3% glioblastomas (36/123) and mostly affected chromosomes 7, 9 and 12, with amplification of oncogenes (EGFR, MDM2/CDK4), and homozygous deletion of tumor suppressor genes (CDKN2A)." (PMID 30542515, 2018). "CDK4 and MDM2 were amplified during differentiation of neural progenitor cells, in neural stem cells, and in glioblastoma." (PMID 29416732, 2018). "By contrast, other genes including CDK4 and MDM4 frequently amplified in glioblastoma were also amplified in human neural progenitor cells during differentiation." (PMID 28415661, 2017).
glioblastoma (continued). "Five moderate to high-level amplified genes in glioblastomas identified in this study, EGFR, PDGFRA, CDK4, MDM2 and CYP27B1, have also been previously reported, sometimes with co-amplification." (PMID 22691727, 2012). "Although CDK4/6 inhibitors have ample BBB penetration, their retention is limited by efflux through ABCB1 and P-gp transporters; hence, clinical trials for glioblastoma have been unsuccessful." (PMID 38212807, 2024). "Since CDK4/6 activates NFκB signalling, we have examined whether blockade of CDK4/6 with palbociclib-MHI 148 conjugate, 1, could activate the endogenous TNFα mediated apoptosis pathway in glioblastoma." (PMID 38212807, 2024). "Understanding PMT regulation more broadly may aid in identifying treatments that preferentially target specific subtypes, as demonstrated for CDK4/6 or EZH2 inhibition for proneural glioblastomas and DGKα or BMI-1 inhibition for mesenchymal glioblastomas." (PMID 38337036, 2024). "Moreover, the analysis of DNA copy number variation of 543 glioblastoma samples shed light on some common amplification events on chromosome 7 (EGFR, MET, CDK6), chromosome 12 (CDK4 and MDM2), and chromosome 4 (PDGFRA)." (PMID 39148319, 2024). "No tumors demonstrated EGFR amplification, MET amplification, CDK4 amplification, MDM2 or MDM4 amplification, PTEN homozygous deletion, or NF1 homozygous deletion that are frequent oncogenic events in conventional IDH-wildtype glioblastomas." (PMID 38079020, 2023). "In glioblastoma cells, high PTK2 expression can increase the expression of CCND1 and CCNE, reduce the expression of CDKN1B (p27Kip1) and p21Waf1, and enhance the activity of CDK4, thereby promoting the G1/S phase transformation of glioblastoma cells." (PMID 36770809, 2023). "Furthermore, a study of the malignant brain tumor glioblastoma multiform (GBM) combined the autophagy inhibitor, MPT0L145, with the CDK4/6 inhibitor abemaciclib." (PMID 35008317, 2021). "However, CDK2/CDK4 and CDK6 expressions were negatively correlated with immune infiltration in glioblastomas and skin cutaneous melanomas." (PMID 33668805, 2021). "The inhibitors of CDK-4 and CDK-6 have shown promise in glioblastoma treatment." (PMID 30038719, 2018). "Recently, we demonstrated synergistic antitumor effects of the CDK4/6 inhibitor abemaciclib and the EZH2 inhibitors GSK126 or tazemetostat in patient-derived glioblastoma (GBM) models." (PMID 40284428, 2025). "The alterations in FGFR4, KIT, and PEG3 were correlated with a short OS in astrocytoma, alterations in CDK4, FUBP1, and NTRK2 were correlated with a short OS in oligodendroglioma, and alterations in CDK4, CIC, FGFR3, and KMT5B were correlated with a short OS in glioblastoma." (PMID 36998447, 2023). "Cyclin-dependent kinases, CDK4 and CDK6, are essential in regulating the cell cycle, which is disrupted in cancers like isocitrate dehydrogenase wild-type glioblastoma (GBM)." (PMID 36033522, 2022).
glioblastoma (continued). "Other studies have shown that co-amplification of CDK4 and MDM2, with or without chromosome 1, gain results in worse overall survival while isolated chromosome 1 or 19 gain without CDK4/MDM2 co-amplification results in somewhat better survival in IDH-wildtype glioblastomas." (PMID 32640746, 2020). "Glioblastoma is one of the most aggressive cancers, although data are not yet mature, preliminary studies do not show a clear-cut benefit of immunotherapy in glioblastoma, while clinical studies have demonstrated that CDK4/6 inhibitor alone was not an effective treatment for recurrent glioblastoma." (PMID 33668805, 2021).
sarcoma (116 papers, 1995 to 2026). A usually aggressive malignant neoplasm of the soft tissue or bone. "Amplification of CDK4 is one molecular hallmark of WD/DD-LPS and is the reason why palbociclib was tested in this specific sarcoma subtype." (PMID 37875500, 2023). "Using mouse xenograft models, we found that the co-overexpression of MDM2 and CDK4 in 5H cells with five additional oncogenic mutations can cause proliferative sarcoma with a DDLPS-like morphology in vivo." (PMID 31160689, 2019). "In patients with sarcomas, high CDK4 expression is associated with shorter overall survival period vs. low CDK4 expression (P < 0.05)." (PMID 29670090, 2018). "In the present study, we report that CDK4 is highly expressed in human synovial sarcoma, and high CDK4 expressions are associated with poor prognosis in sarcomas patients and the clinical stage and the TNM grade in synovial sarcoma patients." (PMID 29670090, 2018). "The genes encoding MDM2 and CDK4 are frequently co-amplified in sarcomas, and inhibitors to both targets are approved or clinically tested for therapy." (PMID 30206211, 2018). "Certain studies have demonstrated that MDM2 and CDK4 were strongly implicated in the pathogenesis of carcinoma and sarcoma." (PMID 23426899, 2013). "Notably, CDK4 has been associated with malignant metastasis and poor prognosis in CS patients and has been identified as a potential therapeutic target in other sarcomas." (PMID 40867318, 2025). "In summary, co-overexpression of MDM2 and CDK4 causes high-grade sarcoma with a DDLLPS-like morphology in transformed human BMSCs by accelerating cell growth and migration, and the blockage of adipogenic potential, after cooperation with multiple genetic factors." (PMID 31160689, 2019). "CDK4, a key molecule in the cell cycle, is associated with favorable prognosis in sarcoma." (PMID 30598078, 2018). "The amplification of the MDM2 gene in sarcomas is often associated with CDK4 amplifications." (PMID 30206211, 2018). "The combination of CDK4/6 inhibitors and immunotherapy against sarcoma is being studied in two ongoing clinical trials." (PMID 40856900, 2025). "On the other hand, the specificity of MDM2 and CDK4 was relatively low, as some sarcomas, including myxofibrosarcoma and undifferentiated pleomorphic sarcoma, also show positivity." (PMID 40078181, 2025). "In sarcomas like OS, CDK4/6 inhibitors such as Palbociclib, Ribociclib, and Abemaciclib have been developed to target CDK4/6 activity." (PMID 40076599, 2025). "Clinical and preclinical studies showed efficacy of CDK4/6 inhibitors in different types of sarcoma." (PMID 40856900, 2025). "Amplification of CDK4, often seen in sarcomas such as OS and liposarcoma, bypasses the need for normal growth signals, allowing tumor cells to proliferate uncontrollably." (PMID 40076599, 2025). "CDK4 inhibitors have demonstrated efficacy in other cancers, including sarcomas such as osteosarcoma." (PMID 40867318, 2025). "CDK4 gene amplification in sarcomas has been observed in both bone and soft tissue tumors, while MDM2 gene amplification predominates in soft tissue tumors, often without coamplification of other genes in the 12q13-q15 region." (PMID 38275873, 2024). "These genomic specificities have fueled the clinical evaluation of selective CDK4/6 inhibitors in sarcomas." (PMID 38434982, 2024). "The inhibition of CDK4/6 also represents a promising precision medicine-guided therapy for other childhood sarcomas." (PMID 36839989, 2023). "From December 2018 to November 2021, 96 patients with advanced and progressing sarcomas were screened for CDK4 and CDKN2A RNA expression in a baseline biopsy and assessed for eligibility." (PMID 37875500, 2023). "Out of eight cases of intermediate sarcomas, two (25%) were positive for both p16 and CDK4, both of which were cases of atypical lipomatous tumors." (PMID 37016649, 2023).